WDR77 (WD repeat domain 77)
Description:
Non-catalytic component of the methylosome complex, composed of PRMT5, WDR77 and CLNS1A, which modifies specific arginines to dimethylarginines in several spliceosomal Sm proteins and histones. This modification targets Sm proteins to the survival of motor neurons (SMN) complex for assembly into small nuclear ribonucleoprotein core particles. Might play a role in transcription regulation. The methylosome complex also methylates the Piwi proteins (PIWIL1, PIWIL2 and PIWIL4), methylation of Piwi proteins being required for the interaction with Tudor domain-containing proteins and subsequent localization to the meiotic nuage.
Synonyms: MEP-50; MEP50; HKMT1069; Nbla10071; p44; p44/Mep50
Tractability: Small molecule: a structure with a bound ligand is known; a high-quality ligand is known. PROTAC: ubiquitination databases record sites on it; its protein half-life has been measured; a small molecule that binds it is known.
Target class: Reader; Epigenetic regulator; Methyl-lysine/arginine binding protein; WDR domain
Gene: Protein-coding gene on chromosome 1 (111,439,890 to 111,449,256, reverse strand). Ensembl gene ENSG00000116455.
Subcellular location: Nucleus; Cytoplasm
Subcellular location (Human Protein Atlas): Cytosol; Nucleoplasm; Golgi apparatus
Pathways (Reactome):
Chromatin organization: RMTs methylate histone arginines
Metabolism of RNA: snRNP Assembly
Gene Ontology:
Molecular function: methyl-CpG binding; protein binding; transcription coactivator activity; ubiquitin-like ligase-substrate adaptor activity
Biological process: positive regulation of mRNA splicing, via spliceosome; positive regulation of rRNA processing; spliceosomal snRNP assembly; positive regulation of DNA-templated transcription; protein polyubiquitination; ubiquitin-dependent protein catabolic process
Cellular component: cytoplasm; cytosol; methylosome; nucleoplasm; nucleus; Golgi apparatus; Cul4B-RING E3 ubiquitin ligase complex; transferase complex
Genetic constraint (gnomAD): Loss-of-function variants: 32 observed, 40.8 expected, observed/expected ratio (o/e) 0.78, 90% interval 0.59 to 1.05. The upper end of that interval is the gene's LOEUF score, 1.05, which puts it in group 4 of 6, group 1 being the genes least tolerant of losing a copy. Missense variants: 389 observed, 395.46 expected, observed/expected ratio (o/e) 0.98, 90% interval 0.9 to 1.07. Synonymous variants: 186 observed, 153.74 expected, observed/expected ratio (o/e) 1.21, 90% interval 1.07 to 1.37.
Homologues: Orthologues: chimpanzee WDR77 (99% identical), rabbit WDR77 (94% identical), dog WDR77 (92% identical), pig WDR77 (91% identical), rat Wdr77 (90% identical), guinea pig WDR77 (90% identical), mouse Wdr77 (90% identical), tropical clawed frog wdr77 (58% identical). Paralogues in human: GEMIN5 (26% identical), WDR24 (19% identical), PEX7 (18% identical), RBBP4 (17% identical), RBBP7 (16% identical), WDR73 (16% identical), GRWD1 (15% identical), WDR59 (15% identical), ERCC8 (11% identical).